HCFC1 (host cell factor C1)
Diseases named in the same sentence as HCFC1 in open-access papers:
HCFC1 is named in the same sentence as 70 diseases in open-access papers, as found by Europe PMC text mining. Sharing a sentence is not in itself a finding about the gene and the disease. The quoted sentences say what the papers report.
Intellectual disability (10 papers, 2013 to 2024). "It is suspected that HCFC1 variants were associated with common epilepsy and the relationships between cobalamin metabolism disorders, intellectual disability and epilepsy remain elusive." (PMID 37264743, 2023). "HCFC1 is involved in control of the cell cycle with mutations in this X-linked (Xq28) gene associated with intellectual disability." (PMID 31323913, 2019). "In humans, HCFC1 resides on Xq28 and has been strongly implicated in development of intellectual disability." (PMID 31207118, 2019). "This hints at possible overlap in downstream disease mechanisms causing intellectual disability in patients bearing OGT or HCFC1 mutations." (PMID 28584052, 2017). "HCFC1 mutations cause intellectual disability by affecting normal brain functioning." (PMID 38025430, 2023). "Mutations in HCFC1 protein are associated with Non syndromic Intellectual Disability in humans." (PMID 34847148, 2021). "We suggest that these cortical malformations observed upon loss of HCF‐1 in subpopulations of GABAergic interneurons and glia may well also be present in human intellectual disability patients carrying HCFC1 mutations." (PMID 31207118, 2019). "Over expression of HCFC1 due to a variant is linked to intellectual disability." (PMID 31323913, 2019). "Such malformations could be one way by which human patients carrying HCFC1 mutations display intellectual disability." (PMID 31207118, 2019). "Several genes, including HCFC1 and MN1, have been reported in the literature, causing intellectual disability of various intensities." (PMID 38956580, 2024). "Other X-linked forms of mental retardation have been reported in patients with mutations in GDI1, CLIC2, HCFC1, and RAB39B." (PMID 23634718, 2013).
cobalamin deficiency (5 papers, 2016 to 2024). "Cobalamin deficiency, or cblX syndrome, is linked to mutations in the HCFC1 gene’s kelch protein interaction domain." (PMID 38956580, 2024). "Mutations in HCFC1 cause cblX syndrome, a multiple congenital anomaly syndrome, associated with cobalamin deficiencies and significant neurological deficits, among other phenotypes." (PMID 32522152, 2020). "The complementation groups cblC, cblD and cblX are caused by mutations in the MMACHC (methylmalonic aciduria (cobalamin deficiency) cblC type, cblC), MMADHC (methylmalonic aciduria (cobalamin deficiency) cblD type, cblD) and the HCFC1 (host cell factor C1, cblX) genes." (PMID 27061115, 2016). "Other mutations in other domains of HCFC1 do not lead to cobalamin deficiency, making these kelch domain mutations rare." (PMID 38956580, 2024). "Our findings raise the possibility that HCFC1 and RONIN deficiency syndromes may be primarily ribosomopathies with the cobalamin deficiency playing a less prominent role." (PMID 35013307, 2022).
homocystinuria (5 papers, 2019 to 2025). An autosomal recessive inherited metabolic disorder caused by mutations in the CBS, MTHFR, MTR, and MTRR genes. "Mutations in Host Cell Factor C1 (HCFC1) transcription factor cause Methylmalonic aciduria and homocystinuria (MIM #309541, also known as Mental retardation, X-linked 3), an X-linked recessive metabolic disorder characterized since early infancy by severe delayed psychomotor development." (PMID 36671555, 2023). "In total, these data demonstrate that, due to loss of HCFC1 or RONIN function, and reduced Mmachc target gene expression, the Hcfc1A115V/Y and RoninF80L/F80L mice are bona fide models of combined methylmalonic acidemia and homocystinuria." (PMID 35013307, 2022).
diabetes (4 papers, 2013 to 2026). "In diabetes mice, hepatic knockdown of O-GlcNAc transferase (OGT) and host cell factor C1 (HCF-1) results in improvement of homeostasis of glucose confirming these as sensor for glucose and gluconeogenesis regulator." (PMID 30258344, 2018).
virus infection (4 papers, 2013 to 2024). "Apart from this similarity, different virus infection pathways owned their unique genes, with STAT1,RSAD2 and IRF9 in the influenza A pathway,IL-2RA,IL-2RB and CD40 in the HTLV-1 infection pathway, HCFC1, MAP3K7, SOCS3, IRF9, HMGN1, and FAS in the herpes simplex infection pathway." (PMID 35795668, 2022). "Second, HCFC1 is known to interact with CREB3, a protein previously shown to be involved in leukocyte migration._ENREF_37 This study further shows that the protein may have a role in cell migration regulation in processes other than virus infection." (PMID 23593504, 2013).
herpes simplex infection (3 papers, 2016 to 2022). "On the other hand, HCFC1 (host cell factor C1), which has a higher WPDMs in women, is associated with herpes simplex infection, which is female dominant." (PMID 27561550, 2016).
partial epilepsy (3 papers, 2023 to 2025). "Mutations in other domains of HCFC1 cause non-syndromic X-linked intellectual disability (XLID) or focal epilepsy." (PMID 41562862, 2025). "The role of HCFC1 variants in partial epilepsy was validated in another cohort from multiple centers." (PMID 37264743, 2023). "We confirmed the role of HCFC1 variants in partial epilepsy in another cohort from multiple centers." (PMID 37264743, 2023). "In conclusion, the present study indicated that HCFC1 was potentially a candidate gene for common idiopathic partial epilepsy with distinct underlying mechanism of the proteolysis dysfunction and loss of growth suppression." (PMID 37264743, 2023). "HCFC1 is potentially a candidate gene for common partial epilepsy with distinct underlying mechanism of proteolysis dysfunction." (PMID 37264743, 2023). "Mutations in the transcriptional co-factor HCFC1 cause methylmalonic aciduria and homocystinemia, cblX type (cblX) (MIM#309541), non-syndromic X-linked intellectual disability (XLID), and focal epilepsy." (PMID 41562862, 2025). "HCFC1 is a potential candidate gene for common partial epilepsy, demonstrating a unique mechanism of proteolysis dysfunction." (PMID 38956580, 2024). "To confirm the association between HCFC1 variants and epilepsy, we collected additional 80 cases with partial epilepsy but without acquired causes from other clinical centers, including 31 trios and 49 singletons." (PMID 37264743, 2023).
epilepsy (2 papers, 2023 to 2025). A brain disorder characterized by episodes of abnormally increased neuronal discharge resulting in transient episodes of sensory or motor neurological dysfunction, or psychic dysfunction. "Together, these efforts promise to unravel the complexity of HCFC1-associated epilepsy and advance personalized treatment paradigms for neurodevelopmental disorders linked to transcriptional co-factor dysfunction." (PMID 41562862, 2025). "In summary, our work positions mTOR as one potential modulator of seizure severity in hcfc1a-deficient zebrafish, offering a mechanistic bridge between HCFC1 dysfunction and epilepsy." (PMID 41562862, 2025). "Disclosing the sub‐molecular effects and establishment of HCFC1‐epilepsy association will help the early diagnosis and management of patients with HCFC1 variants." (PMID 37264743, 2023). "The present study suggested that HCFC1 was potentially a candidate pathogenic gene of common epilepsy with distinct mechanism of proteolysis dysfunction." (PMID 37264743, 2023). "This study aimed to explore the role of HCFC1 variants in common epilepsy and the mechanism underlying phenotype heterogeneity." (PMID 37264743, 2023). "Nonsense mutation of murine HCfC1 in a sub-population of NPCs resulted in increased cell death and reduced GABAergic cells, the primary inhibitory cells of the central nervous system, whose dysfunction has been implicated in epilepsy and seizures." (PMID 41562862, 2025). "Prior work linking HCFC1 mutations to GABAergic deficits in mice and radial glial abnormalities in zebrafish suggest a multifaceted mechanism, wherein mTOR may underlie neurodevelopmental phenotypes and potentially intractable epilepsy in cblX syndrome and other HCFC1-related seizure disorders." (PMID 41562862, 2025).
methylmalonic acidemia (2 papers, 2022 to 2025). A genetically heterogenous inherited disorder characterized by abnormalities in the metabolism of lipids and proteins. "Combined methylmalonic acidemia (MMA) and hyperhomocysteinemias are inborn errors of vitamin B12 metabolism, and mutations in the transcriptional regulators HCFC1 and RONIN (THAP11) underlie some forms of these disorders." (PMID 35013307, 2022).
microcephaly (2 papers, 2016 to 2019). A congenital or acquired developmental disorder in which the circumference of the head is smaller than normal for the person's age and sex. "Like homozygous carriers of BOD1 mutations, individuals affected by HCFC1 mutations show no microcephaly phenotype." (PMID 27166630, 2016).
steatosis (2 papers, 2019 to 2025). Increased lipid within the cytoplasm of cells. "The hepatocyte-specific heterozygous Hcfc1 knockout in Hcfc1hepKO/+ females models rapid resolution of liver injury characterized by steatosis and fibrosis as well as inflammation." (PMID 30559308, 2019). "The hepatocyte-specific Hcfc1 knockout in Hcfc1hepKO/Y males models the development of terminal NASH characterized by increased steatosis, mitochondrial defects, increased inflammation and cell death, hepatocyte ballooning, fibrosis, progenitor cell activation, and metabolic dysfunction." (PMID 30559308, 2019).
X-linked intellectual disability (2 papers, 2016 to 2025). "The protein was recently found associated with SET1B complexes, COMPASS-like H3K3 histone methyltransferase multisubunit complexes, also containing HCFC1, implicated in X-linked Intellectual Disability." (PMID 27166630, 2016).
ACTHomas (1 paper, 2020). "Additionally, whole exome sequencing (WES) analysis revealed several other mutations associated with ACTHomas, including those in the NR3C1, DAXX, ATRX, and HCFC1 genes." (PMID 33266265, 2020).
Ataxia (1 paper, 2021). Ataxia refers to impaired coordination of voluntary muscle movement. "Second, Hcf1 (herein referring to Hcfc1), which is a binding partner of Ronin, was found to be part of the ataxia protein-protein interaction network, and has been broadly implicated in neurodevelopmental disorders, including non-syndromic X-linked mental retardation." (PMID 34165550, 2021).
Epileptic encephalopathy (1 paper, 2023). A condition in which epileptiform abnormalities are believed to contribute to the progressive disturbance in cerebral function. "The HCFC1 variants within the proteolysis domain disrupted the proteolytic processing with loss of growth suppression but did not affect MMACHC expression that was associated with cobalamin disorder and severe epileptic encephalopathy." (PMID 37264743, 2023).
generalized epilepsies (1 paper, 2023). "No hemizygous or homozygous HCFC1 variants were identified in the 150 patients with idiopathic generalized epilepsies." (PMID 37264743, 2023).
heart malformations (1 paper, 2022). "The cause of death in both the Ronin and Hcfc1 mutants is currently unclear, but the congenital heart malformations are a possible explanation as conditional knockout of Ronin in developing cardiomyocytes resulted in lethality by E13.552." (PMID 35013307, 2022).
intellectual impairment (1 paper, 2024). "Previous studies have established a connection between HCFC1 gene mutations and syndromic (cblX) and non-syndromic forms of intellectual impairment." (PMID 38956580, 2024). "To date, 16 different mutations in HCFC1 have been associated with various neurological abnormalities, including intellectual impairment, and the protein is involved in cellular growth and metabolism." (PMID 38956580, 2024). "For instance, HCFC1 promoter region mutations cause intellectual impairment but no cobalamin-related symptoms." (PMID 38956580, 2024).
lung adenocarcinoma (1 paper, 2023). A carcinoma that arises from the lung and is characterized by the presence of malignant glandular epithelial cells. "HCFC1 is involved in the control of cell cycle and it has been reported to be overexpressed in lung adenocarcinomas." (PMID 37843125, 2023).
non-small cell lung carcinoma (1 paper, 2023). A group of at least three distinct histological types of lung cancer, including non-small cell squamous cell carcinoma, adenocarcinoma, and large cell carcinoma. "Downregulation of HCFC1 correlated with Circadian rhythm mammal and non-small cell lung cancer." (PMID 37283799, 2023).
prostate carcinoma (1 paper, 2023). A carcinoma that arises from epithelial cells of the prostate gland. "HCFC1 also plays a non-negligible role in various types of cancers, such as renal cell carcinoma, cervical cancer, prostate cancer, and myeloid malignancies 21-23." (PMID 37283799, 2023).
Siderius type X-linked mental retardation (1 paper, 2024). "Pathogenic variants in the HCFC1 gene cause X-linked mental retardation syndrome, also known as Siderius type X-linked mental retardation." (PMID 38956580, 2024).
cancer (22 papers, 2014 to 2025). A tumor composed of atypical neoplastic, often pleomorphic cells that invade other tissues. "The remaining three patient-specific mutations (ACD p.G223V, DOT1L p.V114F, HCFC1 p.Y103H) were novel mutations previously undescribed in public cancer databases." (PMID 26345285, 2015). "In accordance with its cancer-promoting role, HCFC1 was found to have an increased activity in UCEC." (PMID 37843125, 2023). "The HCFC1 transcription factor has an immunomodulatory role in cancer by inhibiting immune responses, and by promoting tumor growth and vascularization." (PMID 37843125, 2023). "Our experiments in vitro validated that downregulation of HCFC1 expression inhibited cell viability, migration, and invasion capacity and promoted apoptosis, suggesting similar to other cancers, HCFC1 can serve as an oncogene and may be a novel target for treatment." (PMID 37283799, 2023). "Identifying a number of putative drivers, ARID1A, CHD4, HCFC1, STAG2, SMARCA4, and NCOR1 are known cancer driver genes." (PMID 37444571, 2023). "Moreover, analysis of HCFC1 binding sites in K562 cells with endogenous BORIS expression showed a strong correlation between HCFC1 and BORIS binding in this cancer cell line." (PMID 38297316, 2024). "The significantly upregulated proteins RAB14 (Ras-related protein Rab-14) and HCFC1 (Host cell factor 1) in IDC and ILC with the ER- and PR-positive, HER2-negative patients (cancer No. 415 and NATs No. 112) were analyzed from mRNA level based on the TCGA database." (PMID 37064116, 2023).
tumor (20 papers, 2013 to 2025). "The associations between HCFC1 expression with somatic mutational signature, tumor mutational burden (TMB), and microsatellite instability (MSI) were investigated." (PMID 37283799, 2023). "Correlation analysis suggested high HCFC1 protein was associated with higher tumor stage (P=0.049), larger tumor size (P=0.032), poor tumor differentiation (P=0.039), vascular invasion (P=0.005), higher recurrence rate (P=0.003) and mortality (P=0.001)." (PMID 37283799, 2023). "Aberrant HCFC1 expression was associated with mutation profiles and tumor immune microenvironment and immune cell infiltration." (PMID 37283799, 2023). "Further study showed that three of the genes, FLNA, KHSRP and HCFC1, also functioned in vivo, and knocking them down caused multifocal tumor in a mouse model." (PMID 23593504, 2013). "Next, we investigate the associations between HCFC1 expression with TMB, MATH, MSI, tumor purity, tumor neoantigen, and homologous recombination deficiency (HRD)." (PMID 37283799, 2023). "Results suggested that higher HCFC1 expression was associated with higher TMB, MATH, MSI, and lower tumor purity levels." (PMID 37283799, 2023). "We next clarify the effects of HCFC1 expression on tumor growth and biological behavior by conducting in vitro experiments." (PMID 37283799, 2023). "HCFC1 expression showed a significant positive association with B cell memory, T cell CD4 memory, macrophage M0, and a significant positive association with immune checkpoint-related gene expression in the tumor microenvironment." (PMID 37283799, 2023). "Noteworthy, with tumor stage and grade increasing, HCFC1 mRNA was gradually increased." (PMID 37283799, 2023). "Furthermore, in HCC patients with early tumor stages (stage I+II) and grades (grade I+II), high HCFC1 mRNA expression still predicted an unsatisfactory prognosis." (PMID 37283799, 2023). "Besides, elevated HCFC1 protein remarkably correlated to higher tumor stage, larger tumor size, poor tumor differentiation, vascular invasion, higher recurrence rate, and mortality." (PMID 37283799, 2023). "Upregulation of HCFC1 expression was associated with TMB, MSI, and tumor purity." (PMID 37283799, 2023). "All results demonstrated that HCFC1 mRNA levels differ widely in different cell types and with a high level of malignant and immune cells, which may be the causes of the HCC immune microenvironment and tumor heterogeneity." (PMID 37283799, 2023). "The mutations in this tumor included 3 predicted high impact mutations in MTOR a regulator of stress response, OGT a glycosyltransferase that modifies a broad range of targets including H2B, AKT1, EZH2, PFKL, KMT2E/MLL5, MAPT/TAU and HCFC1, and FAM129B a negative regulator of apoptosis." (PMID 28415633, 2017). "There were no major changes in matrisome-associated proteins, except for the observed increase in the secreted factor HCFC1 and the ECM-affiliated protein, LGALS3, on the MDA-MB-231-seeded tumor scaffold." (PMID 35755802, 2022).
infection (13 papers, 2007 to 2024). The state of being infected such as from the introduction of a foreign agent such as serum, vaccine, antigenic substance or organism. "RNAP II S2P and HCFC1 amounts consistently decreased as the infection progressed, revealing different requirements for RNAP II S5P, RNAP II S2P, and HCFC1 at different infection stages." (PMID 37500668, 2023).
metabolic disorder (3 papers, 2019 to 2023). "The majority of the literature focuses primarily on the function of HCFC1 at the MMACHC promoter in the human syndrome, cblX. cblX disorder is the result of mutations in the HCFC1 gene and these mutations disrupt protein function causing a decrease the expression of MMACHC and a metabolic disorder." (PMID 32522152, 2020).
brain disease (1 paper, 2025). "hcfc1a is one conserved ortholog of HCFC1 and, therefore, represents a putative system to study the function of HCFC1 in brain disease." (PMID 41562862, 2025).
movement disorder (1 paper, 2020). Neurological conditions resulting in abnormal voluntary or involuntary movement, which may impact the speed, fluency, quality and ease of movement. "However, mutation of HCFC1 in patients with cblX syndrome is associated with movement disorders." (PMID 32522152, 2020).
HCFC1 also shares sentences with these, for which no sentence is quoted: breast carcinoma (4 papers); cervical cancer (4); autism (3); Insulin resistance (3); neurodevelopmental disorder (3); uveal melanoma (3); Burkitt lymphoma (2); latent infection (2); Mental retardation, X-linked 3 (2); Methylmalonic aciduria (2); acute myelogenous leukemia (1); Arrhythmia (1); autism spectrum disorder (1); breast tumors (1); cblC (1); chromoblastomycosis (1); colon cancer (1); Cornelia de Lange syndrome (1); dengue (1); dermatophytosis (1); Dystonia (1); glioblastoma (1); heart defects (1); hematological malignancies (1); Hepatic steatosis (1); hepatocellular carcinoma (1); homocystinemia (1); hyperhomocysteinemia (1); insulinoma (1); leukaemia (1).
A further 12 diseases each share a sentence with HCFC1 in 1 paper.